CFAP251 (cilia and flagella associated protein 251)
Description:
Involved in spermatozoa motility. May also regulate cilium motility through its role in the assembly of the axonemal radial spokes (By similarity).
Synonyms: WDR66; MGC33630; CaM-IP4; SPGF33
Tractability: Small molecule: a structure with a bound ligand is known. PROTAC: ubiquitination databases record sites on it.
Gene: Protein-coding gene on chromosome 12 (121,918,574 to 122,003,927, forward strand). Ensembl gene ENSG00000158023.
Subcellular location: Cytoplasm, cytoskeleton, cilium axoneme; Cell projection, cilium, flagellum
Subcellular location (Human Protein Atlas): End piece; Mid piece
Gene Ontology:
Biological process: flagellated sperm motility; cilium movement
Cellular component: sperm end piece; sperm flagellum; sperm midpiece; axoneme; motile cilium; radial spoke stalk
Genetic constraint (gnomAD): Loss-of-function variants: 82 observed, 118.83 expected, observed/expected ratio (o/e) 0.69, 90% interval 0.58 to 0.83. The upper end of that interval is the gene's LOEUF score, 0.83, which puts it in group 3 of 6, group 1 being the genes least tolerant of losing a copy. Missense variants: 1,226 observed, 1,393.3 expected, observed/expected ratio (o/e) 0.88, 90% interval 0.84 to 0.92. Synonymous variants: 485 observed, 505.45 expected, observed/expected ratio (o/e) 0.96, 90% interval 0.89 to 1.03.
Homologues: Orthologues: chimpanzee CFAP251 (99% identical), dog CFAP251 (78% identical), rabbit CFAP251 (75% identical), mouse Cfap251 (72% identical), tropical clawed frog cfap251 (43% identical), zebrafish cfap251 (37% identical), rat Cfap251 (24% identical). Paralogues in human: EML5 (15% identical), EML6 (14% identical), CFAP44 (13% identical), EML4 (13% identical), EML1 (13% identical), EML3 (12% identical), WDR90 (12% identical), EML2 (11% identical), CFAP52 (9% identical).
Diseases named in the same sentence as CFAP251 in open-access papers:
CFAP251 is named in the same sentence as 9 diseases in open-access papers, as found by Europe PMC text mining. Sharing a sentence is not in itself a finding about the gene and the disease. The quoted sentences say what the papers report.
male infertility (7 papers, 2020 to 2026). The inability of the male to effect fertilization of an ovum after a specified period of unprotected intercourse. "In humans, mutations in genes encoding CFAP61, CFAP91/AAT1/MAATS1/C3orf15, or CFAP251/WDR66 cause male infertility." (PMID 36552811, 2022). "This study aimed to elucidate the pathogenic mechanism linking CFAP251 deficiency to human male infertility and to determine whether CFAP251 plays an active role in both flagella and cilia across species." (PMID 41943837, 2026). "It is currently not known whether mutations in CFAP52 affect male fertility although mutations in WD-repeat proteins, as e.g. in WDR66/CFAP251, WDR96/CFAP43, and WDR52/CFAP54, causing human male infertility due to the sperm flagella defects have been reported." (PMID 32859975, 2020). "Damaging mutations in genes encoding RS1 and RS2 components cause PCD, while mutations in genes encoding RS3 proteins, CFAP61, CFAP91, CFAP251, and LRRC23 result in male infertility but not PCD." (PMID 40886204, 2025). "Strikingly, in mice and humans, mutations in CFAP61, CFAP91, CFAP251, and LRRC23 cause male infertility but not primary ciliary dyskinesia or hydrocephalus, suggesting more differences in the RS3 structure and/or function between sperm flagellum and cilia in multiciliated cells." (PMID 40886204, 2025).
infertile (3 papers, 2022 to 2025). "For example, WES of infertile males without PCD symptoms identified mutations in CFAP251 and CFAP61." (PMID 38091523, 2023).
CFAP251 also shares sentences with these, for which no sentence is quoted: tumor (5 papers); osteosarcoma (4); cancer (2); dysplasia of fibrous (1); esophageal squamous cell carcinoma (1); gastric cancer (1); squamous carcinoma (1).